IL33 (interleukin 33)
Diseases named in the same sentence as IL33 in open-access papers (continued):
Sharing a sentence is not in itself a finding about the gene and the disease.
asthma (continued). "HEK293 cells carrying both asthma extracellular and TIR domain IL1RL1 risk haplotypes presented maximal IL33‐driven signalling, with minimal signalling after IL‐33 activation in other protective haplotypes." (PMID 39301832, 2024). "Monoclonal anti‐IL‐33 antibodies reduce exacerbation in patients with moderate‐to‐severe COPD10 or moderate‐to‐severe asthma." (PMID 38652015, 2024). "Itepekimab is an anti-IL-33 mAb that improved FEV1 compared with placebo after 12 weeks of treatment in patients with moderate-to-severe asthma." (PMID 38609094, 2024). "When subjects with asthma have been challenged with an inhalational allergen, IL-33 is ascending in the bronchial epithelium." (PMID 38650035, 2024). "IL-33 also stimulates lung CD8 (+) cytotoxic T (Tc) cells to produce type 2 cytokines, which are particularly implicated in severe asthma and asthma exacerbations." (PMID 39301028, 2024). "In patients with asthma with varying BMIs, lower IL-33 levels were found in individuals with obesity, although this difference was not statistically significant." (PMID 39171751, 2024). "Elevated levels of IL-33 have been found in patients with severe asthma, allergic rhinitis, and conjunctivitis." (PMID 38787044, 2024). "In a murine model of steroid-resistant asthma, multipotent ILC2s induced by IL-33, TSLP, and IL-2/IL-7 were found to contribute to steroid resistance." (PMID 39194521, 2024). "Regarding asthma, the most widely studied alarmins include IL-25, IL-33, and thymic stromal lymphopoietin (TSLP), which can all drive allergic inflammation via stimulation of TH2 cells and ILC2." (PMID 38878250, 2024). "Airway levels of both TSLP and IL-33 are elevated in patients with asthma compared with healthy individuals and correlate with disease severity." (PMID 38609094, 2024). "Interleukin-33 (IL-33), which is elevated in patients with asthma, promotes Th2-type immune responses." (PMID 39759495, 2024). "In a placebo-controlled 4-arm trial, itepekimab, a monoclonal antibody against IL-33, was found to be efficacious for asthma control and improving lung function compared to the placebo." (PMID 39194521, 2024). "For example, IL1RL1/IL18R1, IL33 and TSLP have emerged as important genes associated with the development of asthma." (PMID 39694589, 2024). "It is commonly known that TSLP and other cytokines generated from epithelial cells, IL-25, and IL-33 are essential in the development of allergic disorders, such as food hypersensitivity, asthma, and AD." (PMID 39057040, 2024). "Three epithelial cytokines, i.e. thymic stromal lymphopoietin (TSLP), IL-33 and IL-25, known as “alarmins”, are central in asthma pathophysiology." (PMID 38609094, 2024). "Genome-wide association studies have also identified several key epithelial-expressed genes and gene networks associated with an increased asthma risk, including TSLP, IL33 and IL1RL1 (an IL-33 receptor)." (PMID 38453256, 2024). "IL-33 induces eosinophilic inflammation and goblet cell hyperplasia in OVA-induced asthma mice model, and IL-33/ST2 axis blockage reduced the total cell and eosinophil count in BALF of allergic asthma." (PMID 39707175, 2024). "These neutrophil serine proteases, released via asthma‐relevant allergens, for example, fungi, house dust mites and viruses, generate several IL33 isoforms detected in the airways and which have biological activity." (PMID 39301832, 2024). "Studies have revealed that airway epithelium-derived cytokines, such as IL-33, serve a central role in T2 inflammation in asthma." (PMID 39707175, 2024). "In BAL samples, asthmatics had higher levels of IL-33, and levels correlated with severity of asthma as judged by airway flow and asthma control test survey scores." (PMID 39200943, 2024). "Several biologic therapies targeting IL-33 signalling are, or have recently been, in development for asthma." (PMID 38609094, 2024).
asthma (continued). "Due to the chronic nature of human asthma and challenges in modeling it accurately, researchers primarily rely on mouse models to investigate the role of IL-33 in activating ILC2s and driving type 2 inflammation in the lungs and airways." (PMID 39301028, 2024). "As IL-33 is upregulated in human asthma and allergy, as well as in related animal models, it is a promising target for therapeutics against allergic inflammatory diseases." (PMID 38890291, 2024). "IL-33, a cytokine derived from epithelial cells, is elevated by allergens in asthma, facilitates the overproduction of ROS, and contributes to airway inflammation." (PMID 37181813, 2023). "In a phase II study including 296 patients with moderate–severe asthma, itepekimab (a human IgG4P mAb against IL-33) was analyzed." (PMID 37762787, 2023). "IL-33 are elevated in asthma; however, a study demonstrated that their levels remain high even after the removal of triggers." (PMID 38082335, 2023). "IL-33 has recently been strongly recognized for its role in asthma and allergic diseases, the earliest manifestations of childhood allergy." (PMID 37545493, 2023). "The main role played by the HMGB1 and IL-33 axis has also been theorised in other experimental models of asthma, such as aspirin-exacerbated respiratory disease (AERD)." (PMID 36675299, 2023). "Results from another phase 2 trial showed that blocking IL-33 with itepekimab resulted in a lower incidence of uncontrolled asthma events compared to placebo, which was close to dupleuximab (22% vs 19%) and improved lung function." (PMID 37377958, 2023). "The Th2 cytokine IL-33 has emerged as a potential smooth muscle effector of remodeling and AHR in asthma due to its association with sub-epithelial thickening and ECM deposition in asthma." (PMID 37773065, 2023). "The enrichment of IL‐33 signatures in neutrophilic (N) and mixed granulocytic (M) asthma sputum transcriptomics was partially replicated in the ADEPT cohort." (PMID 35986608, 2023). "House dust mites (HDM) are clinical allergens that trigger asthma worldwide, promoting IL-33 secretion by epithelial cells, and participating in the development and progression of allergic diseases." (PMID 36834541, 2023). "The bronchial epithelium integrates complex inflammatory and remodeling processes in asthma by releasing IL-25, IL-33, and thymic stromal lymphopoietin (TSLP)." (PMID 37635231, 2023). "After analysis, the high-frequency keywords of IL-33 research related to molecular biology (sST2, IL-1), immunological effects (type 2 immunity, Th2 cells), and diseases (asthma, cancer, cardiovascular diseases)." (PMID 37153553, 2023). "There are a few ongoing phase 2 trials investigating biological drugs targeting IL-33 or its ST2 receptors in the context of severe asthma." (PMID 38203353, 2023). "Periostin is an extracellular matrix protein with an upregulated expression in airway epithelial cells and fibroblasts after activation by IL-13 and alarmin IL-33 in patients with some types of asthma and allergic inflammation, but also in pulmonary fibrosis." (PMID 40980110, 2023). "A recent study demonstrated that genetic variations in IL1RL1 are strongly associated with asthma, revealing that IL1RL1 acts as an essential driver of type 2 immune responses to IL-33." (PMID 37206297, 2023). "Inhibition of the upstream alarmin IL-33 using a monoclonal antibody also reduced FeNO levels in 296 patients with moderate-to-severe asthma." (PMID 40980110, 2023). "Our findings showed that asthma patients were likely to have higher serum levels of IL‐33, compared to HCs (SMD = 2.06, 95% CI: 1.12−3.00)." (PMID 37102668, 2023). "IL-33 expression is often upregulated in allergic and respiratory diseases such as asthma, chronic obstructive pulmonary disease, and allergic rhinitis." (PMID 37153553, 2023).
asthma (continued). "In a Japanese cohort study, low serum IL-33 levels, low peak expiratory flow variability over 1 week, childhood onset of asthma (at age <10 years), and high serum IL-10 levels were associated with a safe reduction in ICS dose." (PMID 40980110, 2023). "Previous studies reported that patients with asthma showed higher levels of interleukin (IL)‐33 in peripheral blood, compared to healthy control (HCs)." (PMID 37102668, 2023). "Several experiments have shown a correlation between asthma, IL-33, non-coding genetic material, and HMGB1." (PMID 36675299, 2023). "We have previously shown that the inflammatory response to S. aureus protease like protein D (SplD) and Alt extract, which are IL-33 dependent asthma models, can vary among different genetic backgrounds in mice." (PMID 37153601, 2023). "In mouse models, prophylactic or therapeutic blockade of IL-33 release attenuated asthma exacerbations." (PMID 37377958, 2023). "Papain is a protease known to cause occupational asthma that also induces asthma-like inflammation in mice via TSLP, IL-33, and ILC2." (PMID 36983043, 2023). "In a genome-wide association study, genetic variants of IL33 and IL1RL1 were significantly associated with asthma." (PMID 36674744, 2023). "In most circumstances, IL-33 plays a pro-inflammatory role in, for example, asthma, inflammatory bowel diseases, and atopic dermatitis." (PMID 38082335, 2023). "In contrast to the primary pathogenic role of 12/15-LOX in asthma, IL-33 administration to Alox15−/− mice results in augmented airway inflammation, suggesting that 12/15-LOX expression is required to limit IL-33-mediated airway inflammation." (PMID 37253655, 2023). "We recently demonstrated the importance of neutrophil proteases in the regulation of IL-33 in a comparable Alt-induced asthma model." (PMID 37153601, 2023). "There are three epithelial cell-derived cytokines such as IL-25, TSLP, and IL-33 known to mediate Th2 inflammation and IL-33 has been identified to initiate type 2 responses in asthma in response to the clinically relevant allergens including HDM." (PMID 37237381, 2023). "In Chinese herbal medicine, Sho-sai-ko-to was reported to relieve OVA-induced asthma symptoms and inhibit IL-33 production in bronchoalveolar lavage fluid in a murine asthma model." (PMID 37834081, 2023). "Upon the intranasal administration of IL‐33, ILC2s accumulate in the lungs and BALF, causing severe asthma." (PMID 37357549, 2023). "In contrast, patients with mild or moderate asthma have less clinical benefit from an IL-33 targeting therapy." (PMID 37153601, 2023). "Treatment of moderate to severe asthma patients with Itepekimab, a mAb targeting IL-33, improved asthma control and quality of life as well as reduced mean blood eosinophil count." (PMID 37163370, 2023). "Some studies have reported that levels of serum sST2, the soluble form of the IL-33 decoy receptor, are elevated in patients with asthma and correlated with disease severity." (PMID 37907612, 2023). "Clinical trials have demonstrated that the human IgG2 monoclonal antibody Astegolimab selectively inhibits the ST2 receptor of IL-33, which can reduce the asthma exacerbation rate (AER)." (PMID 37892176, 2023). "IL‐33 mRNA and protein expression is elevated in the airways of SA patients, with a greater release of IL‐33 in vivo during rhinovirus‐induced asthma exacerbations." (PMID 35986608, 2023). "Meanwhile, this meta‐analysis revealed that the serum levels of IL‐33 were higher in moderate and severe asthma patients compared to that in mild asthma patients (SMD = 0.78, 95% CI: 0.41−1.16)." (PMID 37102668, 2023). "Another phase two trial with Itepekimab, a mAb targeting IL-33, showed similar results with improvement of lung function in patients with moderate-to-severe asthma (NCT03387852)." (PMID 36830772, 2023).
asthma (continued). "Inhibition of IL-13 yielded no reduction in airway eosinophils in 64 patients with uncontrolled asthma, however inhibition of alarmin IL-33 reduced blood eosinophil counts in 296 patients with moderate-to-severe asthma." (PMID 40980110, 2023). "Peripheral blood IL-6 has recently been identified as a potential biomarker for adult asthma, and IL-33 is a susceptibility gene for childhood asthma, while TSLP is associated with initiation and persistence of inflammatory pathways in asthma." (PMID 38106417, 2023). "While most of the FDA-approved biological therapies target pathways of T2 inflammation downstream of T-helper 2 cell activation, modest asthma control has led researchers to study upstream alarmin cytokines, including IL-25, IL-33, and TSLP." (PMID 38259298, 2023). "In virus-induced asthma progression, IL-33 drives asthma exacerbation primarily by dampening innate and adaptive TH1 and cytotoxic responses." (PMID 38082335, 2023). "Using IL‐33 receptor‐deficient mice or treating mice with soluble IL‐33 receptor or anti‐IL‐33 antibody, allergic inflammation was alleviated in patients with asthma." (PMID 37357549, 2023). "We obtained cell‐specific IL‐33‐up‐regulated gene signatures from various cells involved in asthma pathogenesis." (PMID 35986608, 2023). "For example, a recent phase II trial showed that Ipetekimab, an anti-IL-33 monoclonal antibody, improved asthma control, lung function, quality of life, and lowered blood eosinophil count." (PMID 38259298, 2023). "Whenshen decoction has long been used in China for the treatment of asthma and has recently been suggested to inhibit airway inflammation in a mouse model of IL-33-induced asthma by inhibiting ILC2 activation." (PMID 38082335, 2023). "Allergens, air pollutants, and respiratory viruses encountered in daily life can exacerbate asthma and promote the release of IL-33." (PMID 37892176, 2023). "IL-33 thus appears to play a central role in severe asthma by promoting the activation of not only Th2 cells, but also inflammatory CD45RO+ ILC2s7 and Tc2 cells." (PMID 37612281, 2023). "In conclusion, the main findings of present meta‐analysis suggested that there was significant correlation between interleukin (IL)‐33 levels and the severity of asthma." (PMID 37102668, 2023). "Osthole, a component of Cnidium, has also been shown to reduce the severe symptoms of Th2-mediated asthma in mice, partly because it inhibits the IL-33/ST2 signaling pathway." (PMID 38082335, 2023). "Some of these HDM-induced effects on single and double-infected cells resulted from aberrant response to HDM in asthma in terms of an increase in IL-33, RGF, TWEAK, MMP12, FTL3G, and M-CSF." (PMID 37087523, 2023). "Itepekimab, a human IgG4P anti-IL-33 monoclonal antibody, improved asthma control, quality of life and lung function in patients with moderate-to-severe asthma." (PMID 37199256, 2023). "In allergic or eosinophilic asthma patients, IL-33 in bronchoalveolar lavage fluid (BALF) correlates with asthma severity." (PMID 37377958, 2023). "In the current study, CpG-ODN treatment reduced the levels of TSLP and IL-33 in smoke-related asthma." (PMID 36834541, 2023). "We observed enrichment of IL‐33‐up‐regulated signatures predominantly in the sputum of asthmatics with neutrophilic or the TAC2 molecular phenotype of asthma." (PMID 35986608, 2023). "Innate cytokines, known as alarmins, specifically TSLP, IL-25, and IL-33, are promising candidates for the development of novel biological therapies against severe asthma." (PMID 38203353, 2023). "Clinically, patients with mild to moderately severe asthma show increased nasal IL-33 levels following HRSV inoculation and this increase correlates with symptom severity and viral load." (PMID 37239461, 2023). "IL−33 levels correlate with clinical asthma severity, and IL33 variants have been implicated in susceptibility to allergic rhinitis and the risk of asthma." (PMID 37545493, 2023).
asthma (continued). "It is encouraged that data from multi‐center, well‐designed and large sample size studies should be conducted for validating the clinical value of IL‐33 on asthma." (PMID 37102668, 2023). "Interleukin-33 (IL-33) levels are increased in lung epithelial cells and blood serum in patients with asthma." (PMID 36735745, 2023). "We showed earlier that different inbred mouse strains respond differently to an IL-33 mediated asthma model, using the bacterial allergen, S. aureus protease-like protein D." (PMID 37153601, 2023). "The expression level of IL-33 in bronchoalveolar lavage fluid of patients with moderate asthma is significantly higher than that of healthy controls and mild asthma patients." (PMID 38082335, 2023). "The aggravation of asthma is distinguished by increased inflammation of the airways, which is controlled by IL-33 that can stimulate lung macrophages." (PMID 36675299, 2023). "In conclusion, the main findings of present meta‐analysis suggested that there was a significant correlation between IL‐33 levels and the severity of asthma." (PMID 37102668, 2023). "Interleukin (IL)‐33 is an upstream regulator of type 2 (T2) eosinophilic inflammation and has been proposed as a key driver of some asthma phenotypes." (PMID 35986608, 2023). "It is well established that IL-33 promotes fibrosis in many pathological settings such as liver fibrosis, pancreatitis, kidney diseases, rheumatoid arthritis, and asthma." (PMID 37611111, 2023). "IL-33 is a member of the IL-1 family, which can be increased in asthma patients and released during virus-induced exacerbations." (PMID 38124753, 2023). "It is known that TNF-α, IL-4, and IL-13 release is triggered by IL-33 and drives the type 2 inflammatory pattern seen in asthma." (PMID 37153601, 2023). "Recent evidence also demonstrated the potential role and effectiveness of new biological drugs directed against specific type 2 alarmin cytokines (i.e., thymic stromal lymphopoietin [TSLP], IL-25, and IL-33) in severe asthma." (PMID 36830772, 2023). "Tezepelumab is a fully human IgG2 mAb directed to the thymic stromal lymphopoietin —a cytokine of the alarmin family that, together with IL-25 and IL-33, is derived from epithelial cells and plays a very important role in the pathogenesis of asthma." (PMID 36836079, 2023). "Subsequent in vitro studies using primary ASM from mild to moderate asthma subjects demonstrated elevated gene and protein expression of baseline and RV-1B-evoked IL-33 when compared to healthy controls." (PMID 37773065, 2023). "In vivo, the release of IL-33 activates ILC2s, which mainly produce IL-5, IL-9, and IL-13, which thus play significant roles in asthma and allergic inflammation." (PMID 38082335, 2023). "And in lung inflammation such as asthma, IL-33 expression increased in epithelial cells and airway smooth muscle cells." (PMID 35634336, 2022). "Another proinflammatory candidate, cytokine Il33, and its receptor Il1rl1 are both upregulated in Mmp3hi HAFs and are characteristic of fibrotic lung diseases, such as asthma." (PMID 35439171, 2022). "Both adjusted and unadjusted results indicated that serum sST2 level, serum IL-33 level, B-EOS percentage, and asthma were associated with CRSwNP endotypes." (PMID 35633657, 2022). "For example, ILC2s in the lungs are involved in responses to viral infection starting in early life and are mediated by IL-33 stimulation, and a stronger cytokine induction in ILC2s corresponds with exacerbation of asthma severity." (PMID 36109558, 2022). "Asthma pathogenesis is strongly influenced by a number of mediators of inflammation, such as IgE, IL-3, IL-4, IL-5, IL-9, IL-13, IL-33 and TSLP, with many more being discovered." (PMID 36561741, 2022). "Previous studies identified an association between asthma susceptibility and a variant in IL17RB as well as IL33 which was also associated across diverse ancestries." (PMID 36685501, 2022).